KRAS (KRas proto-oncogene, GTPase)
Diseases named in the same sentence as KRAS in open-access papers (continued):
Sharing a sentence is not in itself a finding about the gene and the disease.
osteosarcoma (32 papers, 2012 to 2025). A usually aggressive malignant bone-forming mesenchymal neoplasm, predominantly affecting adolescents and young adults. "Here, we discovered that daraxonrasib selectively inhibits the invasive and proliferative abilities of osteosarcoma cells with KRAS mutations." (PMID 40779492, 2025). "In osteosarcoma, KRAS mutations are key drivers of invasion, angiogenesis, metastasis and cell proliferation, hence affecting the disease’s aggressiveness." (PMID 41479782, 2025). "The targeted anti-cancer effect of daraxonrasib highlights its potential as a therapeutic agent for osteosarcoma patients with KRAS mutations." (PMID 40779492, 2025). "Although oncogenic KRAS mutations are rare in human osteosarcoma, they have been previously reported." (PMID 40779492, 2025). "KRAS mutations, which induce proliferative signaling driving many human cancers, are detectable in a small subset of osteosarcoma patients." (PMID 40779492, 2025). "Daraxonrasib is a promising agent for treating osteosarcoma with KRAS mutations." (PMID 40779492, 2025). "The miR-134–5p/KRAS Axis was strongly associated with the Development of osteosarcoma." (PMID 36545680, 2022). "Many studies have demonstrated that KRAS gene mutations are associated with osteosarcoma." (PMID 31327761, 2019). "We further demonstrated that daraxonrasib inhibition of osteosarcoma depended on the ratio of the active form of KRAS, as demonstrated by the increased daraxonrasib sensitivity of HOS cells that was induced by knockdown of RASA1." (PMID 40779492, 2025). "The extent to which KRAS-mutant osteosarcoma cells are sensitive to KRAS inhibitors remains to be determined." (PMID 40779492, 2025). "In this study, we employed two osteosarcoma cell lines, HOS and HOS-143B, to understand the mechanism of how daraxonrasib affects osteosarcoma with KRAS WT versus the oncogenic mutation KRAS G12S." (PMID 40779492, 2025). "Since daraxonrasib selectively inhibited the cytotoxicity and metastatic ability of HOS-143B, it was expected to selectively inhibit the phosphorylation of ERK1/2 in osteosarcoma cells with mutant KRAS." (PMID 40779492, 2025). "To address the effect of daraxonrasib on KRAS WT and mutant osteosarcoma, we examined the cytotoxicity of daraxonrasib in HOS and 143B cell lines." (PMID 40779492, 2025). "We assayed the effects of treatment on downstream targets using qPCR, immunoblotting, and activity assays to explore the underlying mechanism by which daraxonrasib selectively suppresses the metastatic potential of KRAS mutant osteosarcoma." (PMID 40779492, 2025). "Based on the present findings, we propose a mechanism by which daraxonrasib suppresses the proliferation and metastatic ability of KRAS mutant osteosarcoma cells by inhibiting overactive AKT/ETS1 signaling." (PMID 40779492, 2025). "The expression level of miR-217 was increased in osteosarcoma cells after quercetin and/or cisplatin exposure, whereas that of its downstream target KRAS was decreased." (PMID 35656022, 2022). "The low-risk group was mainly involved in estrogen response early and KRAS signaling pathway, which are important for oncogene of osteosarcoma." (PMID 35978902, 2022). "Both the protein and mRNA levels of KRAS were significantly higher in osteosarcoma tissues and osteosarcoma cells than in adjacent tissues and hFOB 1.19 cells." (PMID 31327761, 2019). "In summary, although further in vivo tests are needed to confirm our results, our data have illustrated that miR-548d-3p can inhibit the growth and migration of osteosarcoma cells by downregulating KRAS." (PMID 31327761, 2019). "A Pearson correlation analysis demonstrated that miR-548d-3p expression correlated negatively with KRAS expression in osteosarcoma tissues." (PMID 31327761, 2019). "Taken together, these data demonstrated that miR-422a exhibited its anti-tumor effects probably through inhibiting the protein expression of BCL2L2 and KRAS in osteosarcoma cells." (PMID 29358307, 2018).
osteosarcoma (continued). "In osteosarcoma, KRAS inhibition decreased MMP1, MMP9, and AKT/ETS1 signaling." (PMID 40779492, 2025). "Finally, we investigated how the increased prevalence of GTP-bound KRAS enhanced the sensitivity of KRAS wild-type osteosarcoma cells to daraxonrasib using siRNA targeting RASA1." (PMID 40779492, 2025). "Studies have proved that KRAS could promote proliferation of osteosarcoma cells and induced cisplatin resistance." (PMID 38087310, 2023). "In addition, The emergence of new targeted drugs targeting classic oncogenes has also provided new options for the treatment of osteosarcoma, such as KRAS." (PMID 38087310, 2023). "In our osteosarcoma samples, KRAS expression correlated negatively with miR-548d-3p expression." (PMID 31327761, 2019). "We therefore assessed KRAS expression in osteosarcoma tissues and cells." (PMID 31327761, 2019). "Previous research in mice and humans has suggested that RAS gene products could be therapeutic targets in cancer, so targeted therapy for KRAS could be a new treatment possibility for osteosarcoma." (PMID 31327761, 2019). "Our in vivo experiments confirmed that the overexpression of miR-548d-3p could suppress the migration of osteosarcoma cells, possibly by inhibiting KRAS." (PMID 31327761, 2019). "We examined whether miR-548d-3p could suppress the growth and migration of osteosarcoma cells by downregulating KRAS, thus providing a new target for the treatment of osteosarcoma." (PMID 31327761, 2019). "In the present study, we evaluated the expression of miR-548d-3p and KRAS in osteosarcoma." (PMID 31327761, 2019). "Therefore, we explored the relationship between miR-422a and its targets BCL2L2 and KRAS in osteosarcoma." (PMID 29358307, 2018). "Furthermore, restoration of miR-422a and knockdown of BCL2L2 and KRAS promoted apoptosis and induce cell cycle arrest in osteosarcoma cells." (PMID 29358307, 2018). "WT KRAS tumors with GAP deficiencies that induce an elevated proportion of active GTP-bound KRAS may be sensitive to daraxonrasib, a possibility that could further expand the use of daraxonrasib for new patient populations with osteosarcoma and beyond." (PMID 40779492, 2025). "It is conceivable that osteosarcoma with KRAS WT can still be affected by daraxonrasib, and that increasing concentrations of daraxonrasib may inhibit the invasive ability of osteosarcomas with wild-type KRAS." (PMID 40779492, 2025). "Thus, we hypothesized that an increase in active KRAS may sensitize osteosarcoma cells with WT KRAS to inhibition by daraxonrasib." (PMID 40779492, 2025). "Moreover, miR-548d-3p treatment downregulated KRAS expression in vivo osteosarcoma tissues." (PMID 31327761, 2019). "Therefore, the modulation of BCL2L2 and KRAS by miR-422a may explain why the down-regulation of miR-422a during osteosarcoma carcinogenesis can promote cancer progression." (PMID 29358307, 2018). "In our previous studies, several target genes were found to participate in the regulation of osteosarcoma, such as BCL-2, PTEN, BCL-xL, and KRAS." (PMID 32152265, 2020). "Thus, we speculate that miR-548d-3p may inhibit osteosarcoma by downregulating KRAS." (PMID 31327761, 2019). "Taken together, these results demonstrated that down-regulated miR-422a promoted the pathogenesis of osteosarcoma by increasing the expression of its target genes BCL2L2 and KRAS." (PMID 29358307, 2018). "The 143B cell line is a derivative of the osteosarcoma cell line HOS, transformed by a KRAS oncogene." (PMID 23688189, 2013). "Osteosarcoma-derived CTCs were assayed for MDM-2 and KRAS amplification, highlighting a difference between patients diagnosed with metastasis in the lung or localized osteosarcoma, thus predicting the onset of metastatic lesions at distant sites and potentially the therapeutic efficacy of drugs." (PMID 34063272, 2021).
osteosarcoma (continued). "Taken together, the present study demonstrates that miR-422a may serve as a tumor suppressor in osteosarcoma via inhibiting BCL2L2 and KRAS translation both in vitro and in vivo." (PMID 29358307, 2018). "This could suggest mislocalization of KRAS within the osteosarcoma system, which could mean it is no longer able to perform its role in propagating the kinase cascade, resulting in interrupted cell signaling." (PMID 40783120, 2025). "In addition, miR-422a decreased the protein expression of BCL2L2 and KRAS while the mRNA levels remained unchanged, suggesting that miR-422a exhibited the anti-tumor effect via regulating BCL2L2 and KRAS protein expression in osteosarcoma cells." (PMID 29358307, 2018). "Finally, the most interesting novel somatic mutations that occurred on trunks and branches were activating mutations of the RAS GTPases KRAS and HRAS that predispose to non‐ossifying fibromas and malignant giant cell tumors of the bone but have not been reported in osteosarcoma thus far." (PMID 33963544, 2021). "This resulted in inhibition of proliferation of osteosarcoma cell lines U-2 OS and HOS, but not of 143B, which harbors a KRAS oncogenic transformation." (PMID 24447333, 2014).
ovarian tumors (32 papers, 2009 to 2026). "Given that the KRAS G12V mutation was exclusively found in the ovarian tumor, the diagnosis was PMP originating from the ovary." (PMID 39310419, 2024). "Only the KRAS G12V mutation was detected in the right ovarian tumor." (PMID 39310419, 2024). "Mutations in KRAS gene are typical of low-grade ovarian tumors while are rare in III and IV stages." (PMID 24063014, 2013). "It is noteworthy that recent studies suggest that KRAS/BRAF mutations play critical roles in the subtyping and prognosis of ovarian tumors, pointing toward future directions for integrating radiomics with molecular biomarkers." (PMID 41601780, 2026). "Our findings revealed that the expression level of KRAS was significantly upregulated in ovarian tumors compared to the control group (p < 0.0001)." (PMID 40913040, 2025). "As for genetic alterations characteristic of less aggressive ovarian tumors, the genes with the highest number of polymorphisms in BOTS and lgOvCa compared to hgOvCa were KRAS, BRAF, and NRAS, which is in line with the scientific literature." (PMID 39456660, 2024). "Since mutations in the MAPK/ERK pathways are common in both borderline and low-grade ovarian cancer and luminal breast cancers the presence of KRAS and BRAF mutations was investigated among the ovarian tumors." (PMID 25226589, 2014). "Hyperactivation of MEK1/2 and ERK1/2 is often caused by activating mutations in Kirsten rat sarcoma viral oncogene homolog (KRAS) and V-Raf murine sarcoma viral oncogene homolog B (BRAF) genes, and therefore was considered to be confined to low-grade ovarian tumors only." (PMID 36362153, 2022). "Our data showed mutual exclusivity between the molecular event of PIK3CA amplification and mutations in PIK3CA, KRAS, BRAF genes, which suggests that each of these alterations may individually be sufficient to drive ovarian tumor pathogenesis independently." (PMID 19638206, 2009). "In OC, KRAS was downregulated, whereas the other hub genes CTNNB1, BRCA1, and JUN were upregulated in ovarian tumor tissues." (PMID 41186627, 2025). "Certain mutations seem to play an important role in BOTS without the BRAF V600E variant (KRAS) and in lgOvCa (KRAS and NRAS), but not in hgOvCa, once again proving that advanced OvCa are molecularly distinct from less aggressive ovarian neoplasms." (PMID 39456660, 2024). "Our previous study demonstrated that although KRAS and BRAF mutations never coexisted within the same ovarian tumor, a defect in one of those genes was present in 6 out of 7 SBOTs examined with the Idylla Mutation Test." (PMID 29682098, 2018).
intrahepatic cholangiocarcinoma (31 papers, 2015 to 2025). A carcinoma that arises from the intrahepatic bile duct epithelium in any site of the intrahepatic biliary tree. "When classified according to tumor subtype, KRAS mutations were identified in 24.9% of patients with intrahepatic cholangiocarcinoma (IHC), in 32.2% of those with extrahepatic cholangiocarcinoma (EHC), and in 9.4% of those with gall-bladder cancer (GB)." (PMID 40499463, 2025). "This study showed that KRAS mutation was observed in 47.4% of the 38 resected patients with hilar cholangiocarcinoma and in 22.2% of the 18 resected patients with intrahepatic cholangiocarcinoma invading the hilum." (PMID 36139531, 2022). "It has been demonstrated that the incidence of KRAS mutations in intrahepatic cholangiocarcinoma and extrahepatic cholangiocarcinoma is 45%-54% and 10%-15%, respectively." (PMID 36686734, 2022). "This cohort study explores the prognostic association of KRAS variant subtypes with survival and recurrence in patients with intrahepatic cholangiocarcinoma." (PMID 34730772, 2022). "In 23% to 50% of intrahepatic cholangiocarcinoma and 30% to 40% of extrahepatic cholangiocarcinoma, the KRAS gene often has mutations, which accelerate tumor progression." (PMID 34367944, 2021). "Although the number of cases was small, it was assumed that MSI-H intrahepatic cholangiocarcinoma may have a good therapeutic effect, even with KRAS mutations." (PMID 40032770, 2025). "Indeed, it has been demonstrated that KRAS mutational frequency is different between intrahepatic cholangiocarcinoma and extrahepatic cholangiocarcinoma." (PMID 36139531, 2022). "What is the prevalence of KRAS variant subtypes and their association with survival and recurrence in patients with surgically treated intrahepatic cholangiocarcinoma (ICC)?" (PMID 34730772, 2022). "This rate may differ according to the anatomical location of the tumor: intrahepatic cholangiocarcinoma is generally associated with a significantly lower rate of KRAS mutation than that observed in patients with extrahepatic cholangiocarcinoma (7–22% vs. 37–46%, respectively)." (PMID 36139531, 2022). "Similar oncogenic drivers, including mutations in KRAS, BRAF, and HER2 (ERBB2), have been identified in intrahepatic cholangiocarcinoma (iCCA)." (PMID 41373672, 2025). "KRAS variants are associated with tumor progression; however, the prevalence of KRAS variant subtypes and their association with survival and recurrence in patients with intrahepatic cholangiocarcinoma (ICC) after curative resection are largely unknown." (PMID 34730772, 2022).